OCLN (occludin)
Diseases named in the same sentence as OCLN in open-access papers (continued):
Sharing a sentence is not in itself a finding about the gene and the disease.
ischemic stroke (continued). "In essence, this study presents a comprehensive review of global research pertaining to the involvement of occludin in BBB damage during ischemic stroke." (PMID 39119484, 2024). "They reported that following ischemic stroke, occludin was broken into two segments of different sizes (31 and 55 kDa) and its amount maintains high until 24 hr." (PMID 40259962, 2024). "This study contributes to this evolving field by employing bibliometric analysis to unravel the intricate landscape of occludin research in the context of BBB damage during ischemic stroke." (PMID 39119484, 2024). "Our study reveals that occludin plays an important role from the acute to the chronic phase after ischemic stroke in vivo." (PMID 36806348, 2023). "The decreased expression of occludin continuously induced BBB dysfunction from the acute to the chronic phase after ischemic stroke." (PMID 36806348, 2023). "Using occludin-deficient mice, the present study elucidated how occludin modulates BBB integrity and neurological function after ischemic stroke." (PMID 36806348, 2023). "Elected levels of MMP12 after ischemic stroke was reported to degrade several tight junction proteins including claudin-5, occludin and ZO-1." (PMID 35382832, 2022). "A previous study suggested that the elevation of serum occludin is important to judge the damage to the blood–brain barrier in ischemic stroke." (PMID 35789538, 2022). "The decrease in TJ proteins, CLDN-5, OCLN, and ZO-1, was observed in ischemic stroke and traumatic brain injury animal models and in TJ-related proteins in animal models of CNS inflammation such as multiple sclerosis." (PMID 35935952, 2022). "Current studies have found that serum occludin is an important marker of BBB destruction in ischemic stroke and is closely related to ischemic stroke." (PMID 35338575, 2022). "As leukocyte migration is known to damage BBB integrity after ischemic stroke, expression of ZO-1 and occludin in the cerebrum was measured by Western blot." (PMID 36052307, 2022). "Genetic deletion of miR-34a effectively reduced the BBB leakage, alleviated the disruption of tight junction proteins ZO-1, claudin-5, and occludin, and improved neurological recovery following ischemic stroke." (PMID 35346266, 2022). "A study reported that MMP-2-mediated degradation of occludin contributes to blood-brain barrier damage in early ischemic stroke." (PMID 33076507, 2020). "Occludin, a crucial tight junction molecule of the BBB which has been implicated in BBB dysfunction in hypoxia and ischemic stroke, also belongs to the tetraspanin family." (PMID 31665089, 2019). "The largest study identified included 458 patients and found that the serum levels of claudin-5, occludin, and the claudin-5-to-ZO-1 ratio were significantly increased in patients with hemorrhagic conversion of ischemic stroke." (PMID 30259344, 2018). "Reports have found that degradation of claudin-5 and occludin can increase the permeability and contribute to brain oedema in ischaemic stroke." (PMID 30170602, 2018). "Remarkably, pharmacological PHD inhibition by treatment with FG-4497 sustained the membrane localization of endothelial occludin and ZO-1, and was sufficient to reduce vasogenic edema formation during ischemic stroke." (PMID 24409307, 2014). "Additionally, our study highlights occludin as a key factor in managing cerebrovascular diseases such as ischemic stroke, suggesting it as a potential therapeutic target for these conditions." (PMID 40313365, 2025). "The three-box graph visually depicts the intricate network of connections among cited references, authors, and author keywords, offering invaluable insights into the role of occludin in the pathogenesis of BBB damage in ischemic stroke spanning the years 2000–2023." (PMID 39119484, 2024). "Notably, our analysis positions occludin as a potential biomarker with significant promise for the early diagnosis of hemorrhagic transformation in ischemic stroke." (PMID 39119484, 2024).
ischemic stroke (continued). "In our findings also occludin gene expression was decreased following induction of ischemic stroke." (PMID 40259962, 2024). "10-O-(N, N-dimethylaminoethyl) ginkgolide B methanesulfonate (XQ-1H) has been shown to normalize the expression of claudin-5, occludin, ZO-1, and β-catenin in ischemic stroke model mice, leading to reduced BBB permeability and protection against oxygen–glucose deprivation/reoxygenation injuries." (PMID 39030617, 2024). "However, little is known about the spatiotemporal expression of occludin during ischemic stroke in a mouse model." (PMID 36806348, 2023). "Recent evidence indicates that autophagy is involved in claudin-5, occludin, and ZO-1 degradation after ischemic stroke and we further examined whether serum exosomes preserved tight junction proteins through autophagy." (PMID 35308117, 2022). "By contributing to tight junctions, the transmembrane proteins Occludin and Claudin-5 as well as the membrane-associated protein ZO-1 in vascular endothelial cells can help maintain or restore BBB integrity, yet they are down-regulated after ischemic stroke." (PMID 32184732, 2020). "Further verifying our findings about the pivotal role of both SDF-1 receptors on stabilizing cellular integrity, inhibition of CXCR4 increased TJP-1, occludin, and claudin 5 in the blood/brain barrier in terms of an ischemic stroke and brain-specific metastasis in lung cancer." (PMID 32210974, 2020). "Moreover, the vitamin D receptor was demonstrated to mediate the protective effect of vitamin D-induced expression of occludin, claudin-5 and zonula occludens in ischemic stroke." (PMID 31930458, 2020). "Furthermore, LXR activation by T0901317 in a mouse model of ischemic stroke selectively prevented the downregulation of occludin and ZO-1 on ischemic microvessels." (PMID 31417573, 2019). "The present study investigates whether the cleaved occludin is released into the blood stream and how blood occludin levels correlate to the extent of BBB damage using a rat model of ischemic stroke." (PMID 28079139, 2017). "Western blot analysis indicated that ruscogenin treatment could upregulate the decreased expressions of ZO-1 and occludin after ischemic stroke in mice." (PMID 27589720, 2016). "Moreover, the level of occludin fragments in serum was correlated with BBB permeability, suggesting that serum occludin levels could reflect the degree of BBB injury after ischemic stroke." (PMID 37721332, 2024). "Therefore, occludin proteins in the blood may serve as a clinically relevant marker of ischemic stroke." (PMID 37840921, 2023). "Occludin plays a key role in maintaining the integrity and permeability of the BBB and it has been reported that modification or loss of occludin expression levels are associated with increase neurological damage in several diseases such as ischemic stroke or status epilepticus." (PMID 37840143, 2023). "After ischemic stroke, fragments of cleaved occludin could release into circulation." (PMID 36032782, 2022). "To verify whether FtMt overexpression increases the BBB integrity by attenuating the degradation of junction-related proteins that occurs after ischemic stroke, we immunofluorescence-stained the tight junctional molecules claudin-5, occludin and ZO-1, along with the endothelial marker CD31." (PMID 35883748, 2022). "Our recent study with a rat model of ischemic stroke showed that occludin degradation occurred in the early phase of ischemic stroke and contributed to BBB disruption, suggesting that occludin might be a potential biomarker for predicting the risk of HT." (PMID 34475814, 2021). "Biomarkers of BBB damage may include vascular-related structural proteins such as fragmented TJ proteins (occludin, claudin-5, and zona occludens), increased cerebral spinal fluid (CSF), and increased occludin levels in the blood as seen following ischemic stroke." (PMID 32397302, 2020).
ischemic stroke (continued). "In summary, our findings demonstrate that blood occludin levels correlate well to ischemic BBB damage in the early stages of ischemic strokes, suggesting that blood occludin levels could be a potential biomarker for assessing risk of ICH following tPA thrombolysis." (PMID 28079139, 2017). "For example, reversing dysbiosis through the ingestion notoginseng saponins restored BBB integrity via increased occludin and Zo1 expression, and reduced proinflammatory cytokine expression (IL-1B, IL-6, TNF) in a rodent model of ischemic stroke." (PMID 40485663, 2025). "We assessed neurological deficits, infarct volume, blood–brain barrier (BBB) permeability, TNF-alpha levels, total oxidant capacity, and gene expressions that play a role in BBB integrity (VEGF, Occludin, and MMP-9) following ischemic stroke." (PMID 39309404, 2024). "The second most cited article titled “Matrix metalloproteinase-2-mediated occludin degradation and caveolin-1-mediated claudin-5 redistribution contribute to BBB damage in the early stage of ischemic stroke” was published in The Journal of Neuroscience." (PMID 39119484, 2024). "Moving forward, continued efforts in elucidating the intricate dynamics of tight junction proteins, including occludin, hold the potential to refine our understanding of BBB regulation in ischemic stroke." (PMID 39119484, 2024). "The post-ischemic dynamics of occludin suggest its importance to the integrity of the BBB and neurological function after ischemic stroke." (PMID 36806348, 2023). "TJPs including ZO-1, Claudin-5, and Occludin are important in regulating the integrity and permeability of BBB and are disrupted and redistributed after ischemic stroke." (PMID 36186136, 2022). "ZO‐1 and occludin expression was significantly decreased on day 1 after MCAO, indicating that the BBB integrity was disrupted after ischemic stroke." (PMID 34156153, 2021). "In particular, tight junctions (TJs) such as Zonula occludens-1 (ZO-1) and occludin play key roles in preventing peripheral leukocyte recruitment and mediating of the function of the BBB following ischemic stroke." (PMID 27589720, 2016). "We also present new evidence showing that the absence of occludin worsens ischemic stroke outcomes in HIV-infected brains." (PMID 40313365, 2025). "Increased expression and activity of several matrix metalloproteases (MMPs; e.g., MMP2 and MMP9) after ischemic stroke contributes to acute BBB damage by cleaving the extracellular domains of several adherens (VE-Cadherin) and tight (Claudin-5, Occludin) junction proteins in BECs." (PMID 41024170, 2025). "Occludin, identified as a linchpin in regulating BBB integrity, proves to be a pivotal player, with implications extending to the diagnosis of hemorrhagic transformation in ischemic stroke." (PMID 39119484, 2024). "Furthermore, overexpression of occludin inhibits both OGD/R and TNFα treated bEnd.3 cell pyroptosis indicates a potential occludin target in BBB disturbance in ischemic stroke." (PMID 36776394, 2022). "In order to further clarify whether the serum occludin levels were the same in the CI and TIA, ischemic stroke patients were divided into two groups." (PMID 33269096, 2020). "The data showed that the level of serum occludin was not significantly different in the two groups, implying that the level of serum occludin did not seem to distinguish the ischemic stroke patients from hemorrhagic stroke patients." (PMID 33269096, 2020). "Ischemic stroke compromises BBB integrity, which is mediated by cytoskeleton rearrangement, and redistribution and disappearance of tight junction proteins such as claudin 5 and occludin in brain endothelial cells, resulting in increased BBB permeability." (PMID 24991401, 2014). "Consistent with our results obtained from ischemic stroke rats, ischemia and reperfusion induced a reduction in occludin protein, but not claudin-5, in wild-type mice, and NBO treatment significantly reversed this reduction." (PMID 22146586, 2011).
ischemic stroke (continued). "PD‐L1 mAb treatment significantly improved ischemic stroke outcomes, particularly in young mice, by reducing infarct volume, enhancing neurological recovery, and preserving BBB integrity through the upregulation of tight junction proteins, including ZO‐1, Claudin‐5, and Occludin." (PMID 40702766, 2025). "However, it is unknown if the degraded or cleaved occludin is released into peripheral circulation and if blood occludin levels correlate to the degree of BBB damage in the early phase of ischemic stroke." (PMID 28079139, 2017). "Consequently, this may not wholly capture the entirety of studies focusing on occludin's role in BBB damage during ischemic stroke." (PMID 39119484, 2024).
ischemia (54 papers, 2012 to 2025). A hypoperfusion of the BLOOD through an organ or tissue caused by a PATHOLOGIC CONSTRICTION or obstruction of its BLOOD VESSELS, or an absence of BLOOD CIRCULATION. "We further investigated the role of ECF-Zn on regulating ECF-MMP-2 activity and occludin loss by utilizing ZnT3-cKO mice with 2h ischemia followed by 4h reperfusion." (PMID 37962463, 2023). "Loss of OCLN expression is closely related to barrier dysfunction in various diseases, such as inflammation and ischemia." (PMID 36733420, 2023). "Western blot data showed that ischemia/reperfusion induced severe occludin loss in the isolated microvessels when compared with sham group." (PMID 37962463, 2023). "Our findings provide evidence that autophagy plays an important role in ischemia-induced occludin degradation and loss of BBB integrity." (PMID 32169114, 2020). "The PCB pretreatment prior to t-PA infusion reduced the loss of occludin and claudin-5 in rats following 2 to 8 hr ischemia." (PMID 29850586, 2018). "In accordance with other studies, our data showed that protein levels of MMP-2 and MMP-9 were induced in an ischemia time-dependent manner, and this change was accompanied by the loss of TJPs occludin and claudin-5." (PMID 29850586, 2018). "Accordingly, ischemia caused a time-dependent loss of occludin and claudin-5 in ischemic tissue after t-PA administration." (PMID 29850586, 2018). "Consistent with Western blot results, prolonged ischemia duration caused greater loss of occludin from the microvessels." (PMID 28079139, 2017). "BBB dysfunction following ischemia is associated with changes in tight junction proteins such as occludin and claudin involving mediators such as matrix metalloproteinases (MMPs) that cause degradation of these tight junction proteins." (PMID 23082218, 2012). "Here we examined whether ischemia-induced occludin loss in microvessel tissues was caused by elevated ECF-Zn levels." (PMID 37962463, 2023). "Our recent study showed that loss of occludin contributed to BBB damage after 2-h ischemia." (PMID 28855859, 2017). "They found that blood Occludin dynamically reflects BBB damage, and NBO attenuates BBB disruption by inhibiting Occludin degradation, thereby improving neurological recovery post-ischemia–reperfusion." (PMID 41154205, 2025). "Based on the results, the ZO-1 and occludin protein expression notably reduced at 24-h post-ischemia compared with sham group (p < 0.01, p < 0.05, respectively)." (PMID 38438409, 2024). "In conditions such as ischemia and lipopolysaccharide-induced injury, Cav-1 expression increases early, contributing to a decrease in claudin-5 and occludin, resulting in the breakdown of the BBB." (PMID 38922036, 2024). "Our findings indicated that, although ischemia/reperfusion injury decreased the expression of ZO-1 and occludin, application of NBP increased such expression." (PMID 36909178, 2023). "In contrast, cerebral ischemia greatly elevated the concentration of ECF-Zn, which then binds to ECF-MMP-2 and activates the enzyme, leading to ischemia-induced occludin degradation and BBB disruption." (PMID 37962463, 2023). "BBB failure can be characterized by reduced levels of TJPs, such as claudin-5 and occludin, after ischemia." (PMID 36445489, 2023). "Detection of TJs also showed that increased expression of ZO-1 and occludin in oeCox7c models, compared to the control group, and oeCox7c also increase these expressions in ischemia/reperfusion models in vivo and in vitro." (PMID 36909178, 2023). "In this study, we found that epalrestat can promote the expression of ZO-1 and occludin in endothelial cells after ischemia both in vivo and in vitro." (PMID 36940077, 2023). "In line with that, further augmentation of RFC1 expression by LV-RFC1 intervention before ischemia salvaged the decreased occludin and collagen-4 levels, otherwise which would be attenuated by ischemia." (PMID 37328777, 2023).